TRAF7 (TNF receptor associated factor 7)
Diseases named in the same sentence as TRAF7 in open-access papers (continued):
Sharing a sentence is not in itself a finding about the gene and the disease.
meningioma (continued). "Next, we focused on the most prevalent genetic alterations reported in meningiomas so far, including NF2, SMARCB1, as well as TRAF7, AKT1, SMO, KLF4, PIK3CA, and TERT in non-NF2 mutated meningiomas." (PMID 31470906, 2019). "Next, we focused on the most common genetic alterations reported so far in meningiomas, including the NF2, SMARCB1, as well as TRAF7, AKT1, SMO, KLF4, PIK3CA, and TERT in non-NF2 mutated meningiomas." (PMID 31470906, 2019). "We also performed Sanger sequencing to check for the presence of mutations previously reported in meningioma driver genes, including regions of NF2, AKT1, TRAF7, KLF4, SMO, and the TERT promoter." (PMID 28552950, 2017). "As a result, most of the previously reported meningioma mutations (NF2, TRAF7, NOTCH2, SMARCB1, CHEK2 and AKT1) were also detected in this study." (PMID 28177878, 2017). "To date, the most common alterations in sporadic meningiomas are NF2 mutations or loss of 22q, with non-NF2 mutant meningiomas harboring mutations in in AKT1, TRAF7, KLF4, POLR2A and SMO16–18." (PMID 28775249, 2017). "We calculated the significance of association of the driver mutations (NF2, SMARCB1, TRAF7/PI3K, TRAF7/KLF4, POLR2A, Hedgehog) with atypical meningiomas." (PMID 28195122, 2017). "Oncogenic mutations in PIK3CA are observed in ~7% of non-NF2-mutant meningiomas, and occur mutually exclusive of AKT1 and SMO mutations, although they frequently co-occur with TRAF7 mutations." (PMID 27458586, 2016). "Next-generation sequencing has characterized recurrent somatic mutations in NF2, TRAF7, KLF4, AKT1, SMO, and PIK3CA, which are collectively present in ~80% of sporadic meningiomas." (PMID 27458586, 2016). "PIK3CA co-mutations are also found in meningiomas with TRAF7 mutations but without KLF4 mutations, and PIK3CA is also associated with activation of mTOR signaling, as with AKT1 alterations." (PMID 41372821, 2025). "A better understanding of the molecular drivers of tumor progression and recurrence, such as the roles of NF2, SMO, AKT1, TRAF7, and KLF4 mutations, will facilitate the development of targeted therapies, potentially improving outcomes for patients with atypical and anaplastic meningiomas." (PMID 41007735, 2025). "A global proteomic analysis revealed unique protein expression patterns in all three genetically distinct meningioma groups AKT1E17K/TRAF7, KLF4K409Q/TRAF7, and NF2−/− when compared to normal meningeal tissue allowing further exploration of these targets for personalised therapy." (PMID 40562609, 2025). "One approach may be to use gene-editing technology such as CRISPR-based systems to target and restore critical TRAF7 function, along with associated alterations like KLF4 point mutations involved in meningioma." (PMID 41372821, 2025). "In summary, mTOR pathway activation via AKT1 or PIK3CA mutations promotes cell proliferation and acts together with TRAF7 dysfunction in meningiomas without KLF4 co-mutations." (PMID 41372821, 2025). "TRAF7 mutations are exclusive to meningiomas without NF2 alterations and are enriched in secretory meningioma." (PMID 41372821, 2025). "Moreover, in MPM and meningioma, TRAF7 and NF2 also exhibit mutually exclusive relationships, which suggests that they are involved in a common signalling cascade." (PMID 38879686, 2024). "Furthermore, several disease-causing mutations, including NF2, TRAF7, KLF4, AKT1 and SMO, have been described in meningiomas and compounds specific for driver mutations are currently under investigation in clinical trials." (PMID 38102708, 2023). "Interestingly, both NF2 and TRAF7 meningiomas possess upregulated genes of canonical members of the fibroblast growth factor (FGF) family." (PMID 36937440, 2023). "Group 1 meningiomas have the best prognosis, are free of NF2 mutations and chromosomal instability, may include AKT1, TRAF7, or KLF4 mutations, and are predicted good responses to cytotoxic therapies." (PMID 38001599, 2023).
meningioma (continued). "All of the described TRAF7 mutations in meningioma are missense, with no nonsense or frameshift mutations." (PMID 36937440, 2023). "Indeed, missense mutations in TRAF7, KLF4, and AKT1 exist in 30%, 14%, and 12% of non-NF2 meningiomas, respectively." (PMID 38001599, 2023). "Meningiomas in the first group are devoid of NF2 alterations and chromosomal instability; may feature AKT1, TRAF7, or KLF4 mutations; have the best prognosis; and are expected to respond to cytotoxic drugs." (PMID 37296907, 2023). "For instance, an increased PD-L1 expression was found in TRAF7-mutated, compared with wild-type skull-base meningiomas, and an increased number of CTLA4+/CD3+ lymphocytes was found in grades 2 and 3 meningiomas harboring the PI3K–AKT–mTOR pathway or SMO mutations." (PMID 35565385, 2022). "In line with previous publications, we could validate the overlap of certain meningioma relevant mutations such as AKT1 and KLF4 with TRAF7 mutations." (PMID 35213082, 2022). "A frequent aberration that can co-occur with TRAF7 is KLF4 mutations in up to 50% of NF2-nonmutated meningiomas of grade 1." (PMID 35565385, 2022). "According to the 2021 WHO brain tumor classification scheme, convexity and the majority of spinal meningiomas have similar molecular findings (loss of chromosome 22q and/or NF2 mutations), while skull base meningiomas demonstrate different mutations (AKT1, TRAF7, SMO, and PIK3CA)." (PMID 36179256, 2022). "It is an extremely slow-growing grade I meningioma cell line, which harbors no broad copy number alterations but carries a single missense mutation (p.G536S) in TRAF7." (PMID 35996584, 2022). "Thus, the roles of both mutant KLF4 and TRAF7 in growth and the secretory clinical manifestation of meningiomas also merit further analyses." (PMID 35996584, 2022). "Found in over 50% of non-NF-2 tumors, TRAF7 mutations independently induce meningioma growth, but more commonly act in combination with one of several co-mutations including KLF4, and ATK1." (PMID 34638590, 2021). "KLF4 K409Q missense mutations are present in up to 50% of NF2 nonmutated meningiomas, often co-present with TRAF7 mutations, and lead to upregulation of HIF-1a pathway." (PMID 34679551, 2021). "TRAF7 mutations is present in about 25% of WHO grade I and II meningiomas." (PMID 34679551, 2021). "In a large cohort, mutations in AKT1 were identified in 38 of 300 non-irradiated meningioma samples (12.6%) and frequently occurred with TRAF7 mutations (25/38 tumors)." (PMID 33346248, 2020). "Unlike NF2, TRAF7 mutations were missense (Q384E, N520S, Q539H, G560C, Y563C, S629T, R653Q), most having been described in meningioma, in correlation with SB location." (PMID 31963394, 2020). "TRAF7 mutations occur in 25% of WHO grade I and II meningiomas." (PMID 33014773, 2020). "Moreover, mutations of NF2 are most frequent in fibroblastic/transitional meningiomas, KLF4 and TRAF7 in secretory meningiomas, and AKT1 mutations in grade I meningothelial meningiomas of the skull base and spine." (PMID 32244473, 2020). "We did observe meningioma-related mutations in oncogenic AKT1, SMO, TRAF7, and NF2 gene." (PMID 32742192, 2020). "Interestingly, in secretory meningioma, a specific genetic signature with simultaneous mutations in the KLF4 transcription factor and the TRAF7 E3 ubiquitin ligase has been found." (PMID 29983887, 2018). "In total, 12–25% of meningiomas grade I were found to have mutations affecting TRAF7, encoding a proapoptotic N-terminal RING and zinc finger domain protein with E3 ubiquitin ligase TNF-receptor associated factor 7 (TRAF7), located on chromosome 16p13." (PMID 30082628, 2018). "We first searched for known meningioma driver mutations in each sample, defining the distribution of benign versus atypical meningiomas in each of the molecular subgroups including NF2, TRAF7 (co-mutated with PI3K pathway or KLF4), Hedgehog and POLR2A mutant tumours." (PMID 28195122, 2017).
meningioma (continued). "In addition, these cell lines also harbored known meningioma driver mutations in neurofibromin 2 (NF2) and TNF receptor-associated factor 7 (TRAF7)." (PMID 28552950, 2017). "While inactivating mutations in NF2 have been described in 30 to 60% of sporadic meningiomas, recent studies have shown that non-NF2 meningiomas harbor activating mutations in SMO (L412F and W535L), AKT1 (E17K), and KLF4 (K409Q), as well as inactivating mutations of TRAF7." (PMID 25347344, 2014). "Overall, TRAF7 alteration activates both tumor supportive (CDC42) and tumor suppressive (KLF4) pathways, and the co-occurrence of TRAF7 and KLF4 mutations allows for hyperactivation of Ras signaling as well as impaired tumor suppression, leading to meningioma growth." (PMID 41372821, 2025). "Furthermore, TRAF7-mutant meningiomas may possess compensatory dependencies on MEK/ERK or JNK pathways, which can be co-inhibited to induce preferential killing." (PMID 40867323, 2025). "Moreover, TRAF7 meningiomas express >5-fold higher levels of VEGFA compared to NF2 tumors, suggesting that VEGFA together with other DEGs from the RAP1 signaling pathway may be responsible for the secretory phenotype of KLF4 meningiomas." (PMID 36937440, 2023). "Of the non-NF-2 gene alterations associated with meningiomas, TRAF7 is the most common." (PMID 34638590, 2021). "In addition to the established association of meningioma with pathogenic aberrations in the tumour suppressor gene NF2, genomic analyses have identified genes including TRAF7, KLF4, AKT1, SMO, PIK3CA and POLR2A to possess recurrent mutations in low grade non-NF2 mutant meningioma." (PMID 33167358, 2020). "Due to lack of secretory meningiomas and TRAF7 mutations in our cohort, the absence of KLF4 K409Q in our cohort may be expected." (PMID 31470906, 2019). "Interestingly, TRAF7 and NF2 mutations are mutually exclusive in malignant pleural mesothelioma as well as in meningioma, suggesting that merlin and TRAF7 may use a common signal transduction pathway." (PMID 29587439, 2018). "Notably, TRAF7/KLF4 mutant meningiomas are the secretory subtype." (PMID 30082628, 2018). "Genomic analysis of meningiomas tissues identified deregulations in the oncogenic genes Phosphoinositide 3-kinase (PIK), RAC-alpha serine/threonine-protein kinase 1 (AKT1), the G protein-coupled receptor smoothened (SMO), TNF receptor-associated factor 7 (TRAF7), and Kruppel-like factor (KLF4)." (PMID 28736504, 2017). "In meningiomas, in addition to histopathological features, alterations in NF2, AKT1, TRAF7, SMO, PIK3CA, KLF4, and SMARCE1 genes are recognised as key biomarkers in molecular classification." (PMID 41009755, 2025). "Additionally, AKT1 is co-mutated in TRAF7-mutated meningiomas without KLF4 mutations." (PMID 41372821, 2025). "A meningioma is a tumor that originated from the meninges with alterations in NF2, AKT1, TRAF7, SMO, and PIK3C, and most meningiomas are benign." (PMID 38540119, 2024). "GO analyses found enrichment of epidermis development and regulation of cell activation pathways in TRAF7 and NF2 meningiomas, respectively." (PMID 36937440, 2023). "To understand how tumor-associated mutations cause meningioma growth and to assess the differences between the most common groups of meningiomas, we compared transcriptomes of NF2 and TRAF7 meningiomas." (PMID 36937440, 2023). "Therefore, there appears to be a strong locational difference (p < 0.0001), suggesting that AKT1-mutant meningiomas arising from the ventral cervical spinal arachnoid are genetically distinct from their intracranial counterparts, based on the relative absence of TRAF7 co-mutation." (PMID 35943573, 2022). "The 2021 WHO classification criteria incorporates 10 genes that are frequently altered in meningiomas, including NF2, AKT1, TRAF7, SMO, PIK3CA." (PMID 35712492, 2022).
meningioma (continued). "A recent study of 469 meningiomas suggested a 22x higher recurrence rate in aggressive subgroups (NF2, PI3K, HH, TRAF7) compared to others (KLF4, POLR2A, SMARCB1)." (PMID 35213082, 2022). "Of note, other common pathological relevant genes of meningiomas, including AKT1 (n = 3; 8%), CDKN2A (n = 2; 5%), SMO (n = 0; 0%), SUFU (n = 0; 0%), POLR2A (n = 6; 16%), TRAF7 (n = 1; 3%), and SMARCB1 (n = 2; 5%), were detected as well." (PMID 34778063, 2021). "Low-grade meningiomas can also present other genetic alterations, particularly affecting SMO, TRAF7, KLF4 AKT1 and PI3KCA." (PMID 34679551, 2021). "Additional common pathological relevant genes of meningiomas, including AKT1 (n = 3; 8%), CDKN2A (n = 2; 5%), SMO (n = 0; 0%), SUFU (n = 0; 0%), POLR2A (n = 6; 16%), TRAF7 (n = 1; 3%), and SMARCB1 (n = 2; 5%), were observed as well." (PMID 34778063, 2021). "However, mutations in TRAF7 can be present in isolation, though often they can co-occur with KLF4, AKT1, or PIK3CA mutations, whereas mutations in SMO and POLR2A are usually mutually exclusive Interestingly, the meningiomas arising from SMO and AKT1-MTOR aberrations often arise in the skull base." (PMID 33194703, 2020). "Meningothelial and transitional meningiomas are more frequently seen in SMO, TRAF7/AKT1, and TRAF7/KLF4 mutant tumors." (PMID 30082628, 2018). "NF2 mutant meningiomas are in all grades including WHO grade II and III whereas SMO, TRAF7, TRAF7/AKT1 and KLF4 meningiomas tend to be WHO grade I." (PMID 30082628, 2018). "A significant interaction between TRAF7 and KLF4 was observed in meningioma." (PMID 40181456, 2025). "Therefore, molecular validation of meningioma findings (e.g., NF2, AKT1, TRAF7) and an increase in both sample size and tumour subtype diversity are important for enhancing the reliability and generalizability of future studies." (PMID 41009755, 2025). "Notably, genetic alterations were not only reported to be frequently found in meningiomas (e.g., NF2 and TRAF7) but also specifically found in each case." (PMID 38238738, 2024). "Meningiomas not defined by NF2 mutations commonly have deletions in CDKN2A/B located on chromosome 9p, as well as TRAF7 mutations on chromosome 16p." (PMID 39796693, 2024). "Furthermore, several typical meningioma locations have distinct related genomic markers (e.g., anterior skull base: SMO, AKT1E17K, TRAF7; central skull base: AKT1, KLF4, TRAF7, POLR2A, Convexity: NF-2, LOH chromosome 22, BAP1)." (PMID 38017560, 2023). "Both TRAF7 and KLF4 alterations in meningioma are loss-of-function mutations and therefore not directly targetable." (PMID 36181606, 2023). "At the time of sequencing, our clinically validated targeted NGS panel did not include several well-known meningioma driver genes (TRAF7, KLF4, or POLR2A), which is a limitation to this study." (PMID 36845294, 2023). "On the other hand, there are no reports of meningiomas with only AKT1 or KLF4 mutations, suggesting that a missense TRAF7 alteration is pre-requisite for AKT1 or KLF4 mutations to cause tumor." (PMID 36937440, 2023). "In our studies, no meningiomas had detectable levels of FGF3 mRNA, except for tumors carrying mutations in TRAF7 and KLF4." (PMID 35996584, 2022). "The combination is intriguing: AKT1/TRAF7 mutations are associated with meningothelial histology and basal localization, while KLF4/TRAF7 mutations are highly specific for secretory meningioma without any predominant localization." (PMID 35984495, 2022). "Genomic sequencing was also performed and mutations in NF2, TRAF7, SMO, KLF4, and AKT1 did not predict RB1 S780 staining or progression in grade 1.5 meningiomas." (PMID 33346248, 2020). "While KLF4 or AKT1 mutations almost always co-occurred with TRAF7 mutations, they did not occur together; SMO-mutated meningiomas all harbored the activating L412F mutation." (PMID 31652973, 2019).
meningioma (continued). "NF2 mutations were found in 44% of the cases, while common genetic alterations in meningiomas of other locations (TRAF7, AKT1, SMO, KLF4, PIK3CA, and TERT) were lacking in non-NF2-associated cases." (PMID 31470906, 2019). "Thus, according to this study, five different molecular subgroups of meningiomas: NF2/SMARCAB1, KLF4/TRAF7, PI3K/TRAF7, Hedgehog, and POLR2A." (PMID 30279357, 2018). "POLR2A-mutant meningiomas do not exhibit mutations in other meningeal driver genes, such as NFE2, TRAF7, KLF4, AKT1, or SMO." (PMID 30279357, 2018). "Of the 88 histologically atypical meningiomas, 75% contained NF2 mutations, while the remaining 9% were TRAF7/PI3K mutant and 16% did not harbour a mutation in the previously established meningioma genes." (PMID 28195122, 2017). "Additionally, alterations in other genes such as SMO, AKT1, TRAF7, and KLF4 have been identified, particularly in non-NF2 mutant meningiomas, indicating a heterogeneous molecular landscape that may influence both prognosis and treatment response." (PMID 41007735, 2025). "However, there are multiple feedback mechanisms that may limit the impact of TRAF7 alterations alone, including those related to KLF4 described in meningioma." (PMID 41372821, 2025). "A combination of KLF4 and TRAF7 genetic mutations, characteristic of secretory meningiomas, has been identified, with KLF4 mutations being unique to this type and not observed in other meningioma variants, indicating high specificity." (PMID 38975554, 2024). "TRAF7 meningiomas were enriched in MAPK (mitogen-activated protein kinases) signaling pathway members, implying that TRAF7 mutants may induce expression of MAPK genes to drive meningioma growth." (PMID 36937440, 2023). "Notably, the PIK3CA-mutant meningiomas lacking mutations in NF2, AKT1, and SMO, tend to express TRAF7 mutations." (PMID 35565385, 2022). "Interestingly, none of the other meningioma subtypes with characteristic alterations, e.g. mutations in NF2, TRAF7/KLF4 or BAP1, or YAP1 fusion, seem to form epigenetic clusters that are distinct to the same extent." (PMID 33319313, 2021). "Similarly, TRAF7 and KLF4 mutations have been linked to meningioma, but were not assessed by the panel of the present study." (PMID 31191822, 2019). "Interestingly, this meningioma subtype was significantly correlated with a lack of NF2 mutations, which suggests that novel mutations in KLF4 and TRAF7 may both be mutually exclusive to alterations in NF2111." (PMID 38879686, 2024). "In contrast to NF2 meningiomas, no obvious oncogenes were present among DEGs upregulated in TRAF7 meningiomas within the “MAPK signaling pathway” set, underscoring the non-aggressive nature of TRAF7 meningiomas." (PMID 36937440, 2023). "While NF2 gene inactivation has long been recognized as a key driver of meningioma tumorigenesis, more recent studies have identified non-NF2 alterations, particularly those involving the TRAKLS genes (TRAF7, AKT1, KLF4, SMO), as well as other genetic changes not otherwise classified." (PMID 40951339, 2025).